LINC01192 (long independently transcribed non-coding RNA 1192)
Synonyms: CT64
Gene: Long non-coding RNA gene on chromosome 3 (163,109,152 to 163,499,037, reverse strand). Ensembl gene ENSG00000241369.
Diseases named in the same sentence as LINC01192 in open-access papers:
LINC01192 is named in the same sentence as 1 disease in open-access papers, as found by Europe PMC text mining. Sharing a sentence is not in itself a finding about the gene and the disease. The quoted sentences say what the papers report.
triple-negative breast carcinoma (1 paper, 2023). An invasive breast carcinoma which is negative for expression of estrogen receptor (ER), progesterone receptor (PR), and human epidermal growth factor receptor 2 (HER2). "In contrast, LINC01192 expression is upregulated in triple-negative breast cancer and is associated with the low survival likelihood of patients with triple-negative breast cancer." (PMID 37379129, 2023).